FURIN (furin, paired basic amino acid cleaving enzyme)
Description:
Ubiquitous endoprotease within constitutive secretory pathways capable of cleavage at the RX(K/R)R consensus motif. Mediates processing of TGFB1, an essential step in TGF-beta-1 activation. Converts through proteolytic cleavage the non-functional Brain natriuretic factor prohormone into its active hormone BNP(1-32). By mediating processing of accessory subunit ATP6AP1/Ac45 of the V-ATPase, regulates the acidification of dense-core secretory granules in islets of Langerhans cells (By similarity). (Microbial infection) Cleaves and activates diphtheria toxin DT. (Microbial infection) Cleaves and activates anthrax toxin protective antigen (PA). (Microbial infection) Cleaves and activates HIV-1 virus Envelope glycoprotein gp160. (Microbial infection) Required for H7N1 and H5N1 influenza virus infection probably by cleaving hemagglutinin. (Microbial infection) Able to cleave S.pneumoniae serine-rich repeat protein PsrP. (Microbial infection) Facilitates human coronaviruses EMC and SARS-CoV-2 infections by proteolytically cleaving the spike protein at the monobasic S1/S2 cleavage site. This cleavage is essential for spike protein-mediated cell-cell fusion and entry into human lung cells. (Microbial infection) Facilitates mumps virus infection by proteolytically cleaving the viral fusion protein F.
Synonyms: PACE; FUR; PCSK3; SPC1
Tractability: Small molecule: a structure with a bound ligand is known; a high-quality ligand is known. Antibody: UniProt places it where antibodies can reach, with high confidence; its Gene Ontology location is reachable by antibodies, with high confidence; UniProt predicts a signal peptide or a membrane-spanning region. PROTAC: ubiquitination databases record sites on it; a small molecule that binds it is known.
Target class: Enzyme; Serine protease S8B subfamily; Serine protease SB clan; Protease; Serine protease
Gene: Protein-coding gene on chromosome 15 (90,868,588 to 90,883,564, forward strand). Ensembl gene ENSG00000140564.
Subcellular location: Golgi apparatus, trans-Golgi network membrane; Cell membrane; Secreted; Endosome membrane
Subcellular location (Human Protein Atlas): Golgi apparatus; Nucleoplasm
Pathways (Reactome):
Disease: Assembly and Release of Dengue Virus Virions; Attachment and Entry; CD163 mediating an anti-inflammatory response; Dengue Virus Attachment and Entry; Induction of Cell-Cell Fusion; Maturation of hRSV A proteins; Potential therapeutics for SARS; Respiratory syncytial virus (RSV) attachment and entry; Synthesis and processing of ENV and VPU; Uptake and function of anthrax toxins
Signal Transduction: NGF processing; Pre-NOTCH Processing in Golgi; SMAD2/SMAD3:SMAD4 heterotrimer regulates transcription; Signaling by PDGF; TGF-beta receptor signaling activates SMADs
Extracellular matrix organization: Activation of Matrix Metalloproteinases; Collagen degradation; Elastic fibre formation
Developmental Biology: Formation of the cornified envelope; Signaling by NODAL
Metabolism of proteins: Amyloid fiber formation; Removal of aminoterminal propeptides from gamma-carboxylated proteins
Cell-Cell communication: Regulation of CDH1 posttranslational processing and trafficking to plasma membrane
Immune System: GBP-mediated host defense
Transport of small molecules: Assembly of active LPL and LIPC lipase complexes
Gene Ontology:
Molecular function: endopeptidase activator activity; endopeptidase activity; endopeptidase inhibitor activity; heparan sulfate binding; heparin binding; nerve growth factor binding; peptidase activity; peptide binding; protease binding; protein binding; serine-type endopeptidase activity; serine-type endopeptidase inhibitor activity; serine-type peptidase activity; signal peptidase activity
Biological process: cholesterol homeostasis; cytokine precursor processing; dibasic protein processing; negative regulation of low-density lipoprotein particle receptor catabolic process; negative regulation of nerve growth factor production; negative regulation of transforming growth factor beta1 production; nerve growth factor production; peptide biosynthetic process; peptide hormone processing; positive regulation of viral entry into host cell; protein maturation; protein processing; regulation of protein catabolic process; secretion by cell; viral life cycle; zymogen activation; amyloid fibril formation; biological process involved in symbiotic interaction; collagen catabolic process; extracellular matrix disassembly; extracellular matrix organization; negative regulation of inflammatory response to antigenic stimulus; plasma lipoprotein particle remodeling; positive regulation of membrane protein ectodomain proteolysis; transforming growth factor beta receptor signaling pathway; and 3 more
Cellular component: cell surface; endoplasmic reticulum; endosome membrane; extracellular exosome; extracellular region; Golgi apparatus; Golgi membrane; membrane; membrane raft; plasma membrane; trans-Golgi network; trans-Golgi network transport vesicle; exocytic vesicle; Golgi lumen
Genetic constraint (gnomAD): Loss-of-function variants: 17 observed, 84.97 expected, observed/expected ratio (o/e) 0.2, 90% interval 0.14 to 0.3. The upper end of that interval is the gene's LOEUF score, 0.3, which puts it in group 1 of 6, group 1 being the genes least tolerant of losing a copy. Missense variants: 877 observed, 1,077.4 expected, observed/expected ratio (o/e) 0.81, 90% interval 0.77 to 0.86. Synonymous variants: 508 observed, 466.59 expected, observed/expected ratio (o/e) 1.09, 90% interval 1.01 to 1.17.
Homologues: Orthologues: chimpanzee FURIN (99% identical), macaque FURIN (99% identical), dog FURIN (96% identical), pig FURIN (95% identical), guinea pig FURIN (95% identical), mouse Furin (94% identical), rat Furin (94% identical), tropical clawed frog furin (70% identical), zebrafish furinb (66% identical), zebrafish furina (66% identical), rabbit FURIN (59% identical). Paralogues in human: PCSK4 (50% identical), PCSK5 (47% identical), PCSK6 (45% identical), PCSK1 (40% identical), PCSK2 (36% identical), PCSK7 (32% identical), MBTPS1 (20% identical), TPP2 (14% identical), PCSK9 (13% identical).
Diseases named in the same sentence as FURIN in open-access papers:
FURIN is named in the same sentence as 115 diseases in open-access papers, as found by Europe PMC text mining. Sharing a sentence is not in itself a finding about the gene and the disease. The quoted sentences say what the papers report.
COVID-19 (34 papers, 2020 to 2025). A disease caused by infection with severe acute respiratory syndrome coronavirus 2. "As expected, genes associated with SARS-CoV-2 viral entry (ACE2, FURIN, and S—spike protein) and viral replication (ORF1ab_REV) were upregulated in the myocardium of patients with COVID-19." (PMID 36968839, 2023). "A significant association of exonic variants in the ACE2, TMPRSS2, and FURIN genes with COVID-19 incidence was detected by another research group using whole-exome sequencing." (PMID 36675784, 2023). "In summary, the present study, based on previous GWAS meta-analyses of COVID-19 susceptibility, hospitalization, and disease severity, partially replicated the implication of a genetic variant in the FURIN gene in SARS-CoV-2 susceptibility." (PMID 36675784, 2023). "We selected rs1894401 in the FURIN gene as a proxy to rs6226 (c.1851G > C), which was examined in a previous meta-analysis of COVID-19 susceptibility." (PMID 36675784, 2023). "Association studies of FURIN gene with COVID-19 prognosis or susceptibility included in the systematic review." (PMID 35432458, 2022). "As SARS-CoV-2 infection has been found to exploit FURIN cleavage, one of the possible implications that should be of interest for further research is the clinical lymphopenia associated with COVID-19 cases." (PMID 34356057, 2021). "According to a multivariable regression analysis, FURIN (C/T + T/T) and TLR2 (T/C + C/C) mutants were associated with COVID-19 susceptibility, with odds ratios of 3.293 and 2.839, respectively." (PMID 38703289, 2024). "We investigated the association of three substantial gene polymorphisms (FURIN, IFNL4, and TLR2) with COVID-19 disease susceptibility and severity to help predict prognosis." (PMID 38703289, 2024). "The FURIN, IFNL4, and TLR2 genotypes and their alleles differed significantly between COVID-19 patients and controls, as well as between patients with severe or critical illness and those with a non-severe presentation." (PMID 38703289, 2024). "Thereby, the present study aimed to investigate the association of three substantial gene polymorphisms (FURIN, IFN4, and TLR2) with COVID-19 susceptibility and severity in Egyptian patients." (PMID 38703289, 2024). "FURIN, IFNL4, and TLR2 gene variants are associated with the risk of COVID-19 occurrence as well as increased severity and poor outcomes in Egyptian patients." (PMID 38703289, 2024). "In conclusion, FURIN, IFNL4, and TLR2 gene variants are associated with the risk of COVID-19 occurrence and linked to increased severity and worse outcomes in Egyptian patients." (PMID 38703289, 2024). "In contrast, in macrophage/monocyte and dendritic cells, the proportion co-expressing NRP1 with CTSL and FURIN was reduced in COVID-19 patients’ lungs." (PMID 35458567, 2022). "The goal of this study was to gain a better insight into the expression of the SARS-CoV-2-related proteins ACE2, TMPRSS2, and FURIN in lung cancer cells, making them susceptible to SARS-CoV-2 infection and potentially affecting the course of COVID-19." (PMID 36077610, 2022). "Here, we present the result of a systematic review and, whenever possible, a meta-analysis of IFITM3, FURIN, ACE1, and TNF-α genetic association with susceptibility to SARS-CoV-2 infection and COVID-19 severity." (PMID 35432458, 2022). "We conducted a systematic review followed by meta-analysis including studies covering genetic association of COVID-19 susceptibility or prognosis with IFITM3, FURIN, ACE1, and TNF-α variants." (PMID 35432458, 2022). "The results show that the proposed combined drugs resulted in a p-value close to 1 between COVID-19 and important affected human genes (such as FURIN, ACE2, etc.)." (PMID 36143492, 2022). "Diabetes and periodontitis increase the expression of ACE-2 where ACE-2, TMPRSS2, and FURIN (highly expressed in the epithelial cells of the oral mucosa) play a crucial role in COVID-19 invasion." (PMID 35224542, 2022).
COVID-19 (continued). "In conclusion, we detected three rare and four ultrarare variants in four COVID-19-related genes, SLC6A20, LZTFL1, XCR1 and FURIN, that are present only in the Brazilian dataset and predicted to affect protein function." (PMID 33824725, 2021). "Several studies have examined the impact of FURIN SNPs on COVID-19-related phenotypes." (PMID 36675784, 2023). "The observed implication of the FURIN gene in COVID-19 susceptibility is not surprising, since it encodes a proprotein convertase that activates various regulatory proteins, including the SARS-CoV-2 spike (S) protein." (PMID 36675784, 2023). "Moreover, studies are still required to adequately evaluate IFITM3, FURIN, and TNF-α genetic variants’ role in COVID-19 susceptibility and outcomes." (PMID 35432458, 2022). "Therefore, we focused our systematic review on IFITM3, FURIN, ACE1, and TNF-α genetic variants and their association with COVID-19 susceptibility and prognosis to reduce unnecessary duplication." (PMID 35432458, 2022). "We identified 230 LUAD/COVID-19 DEGs and constructed a risk score containing 7 genes (BTK, CCL20, FURIN, LDHA, TRPA1, ZIC5, and SDK1) that could classify LUAD patients into two risk groups." (PMID 35733175, 2022). "However, the relationship between these molecules has to be analyzed and further experimentally validated concerning the possible targeting of ACE2/DPP4 and FURIN/ADAM17-related factors in diseased COVID-19 patients." (PMID 33796097, 2021). "Therefore, Notch activity is indirectly involved in COVID-19 infectivity through FURIN induction and shared activation axis of ACE2, both of which aid in viral entry." (PMID 34124207, 2021). "Intriguingly, FURIN expression was increased in CD4+ T-cells from severe COVID-19 patients." (PMID 33178221, 2020). "Another study detected deleterious variants in FURIN, also including rs6226, suggesting a decrease in FURIN protease function that potentially can reduce the risk of SARS-CoV-2, which may explain COVID-19 clinical disparity in Middle Eastern populations (Kuwait, Qatar, and Iran)." (PMID 38703289, 2024). "Compared to the healthy donors, the proportion of macrophage/monocyte cells expressing CD209-CTSL and FURIN was increased, whereas the proportion of dendritic cells expressing CD209-CTSL was unchanged in COVID-19 patients’ lungs." (PMID 35458567, 2022). "We then examined the relationship between TMPRSS2 and other targets for COVID-19 therapy, including ACE2, AXL, CTSL and FURIN." (PMID 35017320, 2022). "TMPRSS2 and ACE2 expression were upregulated in COVID-19 patients but BSG, CTSL, FURIN expression was higher in IPF patients, suggesting their role in increased myofibroblast expression in COVID-19." (PMID 36248845, 2022). "Further analysis of the correlation with invasion genes showed that the entry factor genes (BSG, FURIN, and CTSL) were positively correlated with the ratio of early EndMT in COVID-19, and CTSL was positively correlated with the ratio of early EndMT in IPF." (PMID 36248845, 2022). "We found that SARS-CoV-2 entry factors, including ACE2, TMPRSS2, FURIN, and NRP1, have elevated expression in nasal squamous cells from male individuals with moderate and severe COVID-19." (PMID 34330889, 2021). "ACE is known as a functional receptor of SARS viruses including SARS-no-CoV2, and the severity of COVID-19 has been associated with the levels of ACE2 and TMPRSS2 co-expression and the proteinase activity of FURIN." (PMID 39273283, 2024). "Interestingly, except for FURIN, the expression level of ACE2, TMPRSS2, and NRP1 were significantly dysregulated in nasal tissues from COVID-19 positive patients." (PMID 33732102, 2021). "These collectively support that FURIN expression is induced in highly activated non-regulatory CD25+CD4+ T-cells in severe COVID-19 patients." (PMID 33178221, 2020).
COVID-19 (continued). "Therefore, the downregulation of ACE2, CD147, FURIN, and TMPRSS2 genes and the upregulation of BMAL1 may offer a therapeutic strategy against COVID-19 and periodontitis." (PMID 36366382, 2022).
Hypertension (15 papers, 2010 to 2026). The presence of chronic increased pressure in the systemic arterial system. "In an early genetic study of 1000 participants of Kazakh and Uyghur Chinese ancestry, the G allele of rs2071410 in FURIN was identified as a possible independent risk factor for hypertension in this population." (PMID 39273186, 2024). "In humans, the genetic polymorphisms in the FURIN gene were demonstrated to be significantly associated with some diabetes-related phenotypes, such as metabolic syndrome and hypertension." (PMID 35399937, 2022). "In humans, polymorphisms of the FURIN gene encoding furin protein have been associated with some diabetic complications, such as metabolic syndrome, hypertension, and coronary artery disease." (PMID 35046896, 2021). "In humans, polymorphisms in the FURIN gene have been associated with metabolic syndrome, hypertension, and coronary artery disease." (PMID 35046896, 2021). "For example, FURIN, whose expression was linked with schizophrenia risk (P = 1.05 × 10−7), was also associated with traits such as high blood pressure and diastolic blood pressure but with the opposite direction of effect." (PMID 33481009, 2021). "To address this issue, we systemically investigated the association between variations of the FURIN gene, hypertension and BP in a Xinjiang Kazakh population." (PMID 20707915, 2010). "The purpose of this study was to systematically investigate the association between genetic variations in the FURIN gene and essential hypertension in a Xinjiang Kazakh population." (PMID 20707915, 2010). "By integrating the eQTL Normalised Effect Size (NES) and GWAS beta values for the same variants, we found that SNPs associated with increased risk of CAD and hypertension were associated with higher FURIN expression in the arteries, suggesting that FURIN is detrimental for these phenotypes." (PMID 36188622, 2022). "Our group has found that hypermethylation at FURIN promoter was associated with an increased risk of hypertension in Chinese adults in the Gusu cohort, but whether it is associated with the risk of diabetes is still unknown." (PMID 35399937, 2022). "Increased FES expression colocalised with increased birth weight, increased ovarian cancer risk and decreased blood pressure along with decreased risk of hypertension and other related cardiovascular events and increased FURIN colocalised with decreased birth weight and increased angina risk." (PMID 33417599, 2021). "In summary, our results indicate that the G allele of 1970C > G in the FURIN gene may be an independent risk factor for hypertension." (PMID 20707915, 2010). "b) By sequencing the functional regions of the FURIN gene in 94 Kazakh hypertensives, we were able to find common and rare SNPs or mutations, both of which are considered to contribute to the pathogenesis of hypertension." (PMID 20707915, 2010). "Our results suggest that the FURIN gene may be a candidate gene involved in human hypertension, and that the G allele of 1970C > G may be a modest risk factor for hypertension in Xinjiang Kazakh and Uygur populations." (PMID 20707915, 2010). "Another case-control study in Xinjiang Kazakh and Uygur populations of Chinese ethnic minority groups demonstrated that rs2071410 in the FURIN gene was significantly associated with hypertension and the G allele of rs2071410 may be a modest risk factor for hypertension." (PMID 35399937, 2022). "In addition, it remains possible that 1970C > G is a mere genetic marker, and it may be that LD with other functional variations within the FURIN gene and other functional polymorphisms play more important roles in hypertension." (PMID 20707915, 2010). "In this study, we systemically investigated the association between genetic variations of the FURIN gene and hypertension in a Xinjiang Kazakh population by screening genetic variations of the FURIN gene, then examining the relations between the representative SNPs and hypertension." (PMID 20707915, 2010).